HIF1A (hypoxia inducible factor 1 subunit alpha)
Diseases named in the same sentence as HIF1A in open-access papers (continued):
Sharing a sentence is not in itself a finding about the gene and the disease.
tumor (continued). "Hypoxic, HIF-1α-activated tumor cells respond to this microenvironmental stress by reprogramming their metabolism to engage the glycoytic pathway, a process that is far less efficient, but does not rely on the presence of oxygen." (PMID 22289741, 2012). "Inhibition of HIF-1α has dramatic effects on tumour vasculature: a dramatic reduction in tumour blood vessel permeability was seen on DCE-MRI in tumour-bearing mice within 2 h of treatment with PX-478." (PMID 22281664, 2012). "Earlier reports have proposed that the tumor-suppressor function of the VHL protein reflects the role of VHL as an ubiquitin ligase of the transcription factor HIF-1α, which is known as a master regulator of hypoxic response." (PMID 22390300, 2012). "Both types of irradiated xenografts showed significantly reduced levels CD31 and increased levels of HIF1α in comparison to untreated tumours." (PMID 22607554, 2012). "S3D), suggesting that the hypoxia-mediated enhancement in the tumour formation was critically dependent on the HIF-1α-mediated transcription." (PMID 23185562, 2012). "We and others have demonstrated that histone deacetylase inhibitors, including vorinostat, can reduce HIF-1α activity in tumor cells." (PMID 22829886, 2012). "In patient tumor tissue of PDA we identified co-localization of the hypoxia marker HIF-1α and of the EMT marker Slug." (PMID 23050024, 2012). "Prostate specific antigen (PSA), one of the androgen receptor target genes involved in tumor invasion, is induced by HIF-1α in prostate cancers." (PMID 23241400, 2012). "When the glucose availability in perinecrotic regions of a micro tumor cord was increased through continuous administration of glucagon by using an osmotic pump, the expression of HIF-1α in these regions was significantly increased." (PMID 23203043, 2012). "Bevacizumab treatment is also known to increase hypoxia in the tumour environment and Hif-1α expression." (PMID 23056178, 2012). "During normoxia, the VHL tumor suppressor targets the hypoxia-inducible factor HIF-1α for ubiquitination and proteasomal degradation." (PMID 23202921, 2012). "In HIF-1α positive regions E-cadherin was down-regulated and Slug up-regulated revealing tumor-hypoxia-induced EMT." (PMID 23050024, 2012). "Since these transcription factors are regulated by HIF-1α; a transcription factor associated with the expression of genes involved in tumor invasion, we studied the effect(s) of HCV glycoproteins on HIF-1α expression." (PMID 22178269, 2012). "HIF-1α is centrally involved in multiple aspects of tumorigenesis including tumor angiogenesis, proliferation, metabolism, metastasis, differentiation, as well as responses to radiation and chemotherapy." (PMID 22754381, 2012). "The proliferation of cancer cells, the infiltration of blood leukocytes into tumor tissues, and activation of HIF-1α were increased, in addition to angiogenesis and lymphangiogenesis in the tumor tissues when cancer cells were co-injected with M2-Mφs." (PMID 22616919, 2012). "On the other hand, dys-regulated c-Myc expressed in cancer cells cooperates with HIF-1α to produce VEGF that is an important mediator of tumor angiogenesis." (PMID 23185562, 2012). "One of the most important of these mechanisms is the modulation of hypoxic adaptation within the tumour microenvironment through the direct promotion of the hypoxia-induced stabilisation of HIF-1α." (PMID 23116199, 2012). "In this review, we will discuss significance of Plk3 in HIF-1α regulation, tumor angiogenesis, and its potential as a therapeutic target for cancer treatment." (PMID 23210979, 2012). "HIF-1α is a heterodimeric transcription factor that is upregulated in hypoxic tumor cells and promotes angiogenesis by enabling transcription of pro-angiogenic genes like VEGF." (PMID 23166790, 2012).
tumor (continued). "Our findings identified that, due to suppression of PTEN by miR-17, HIF-1α was stabilized when tumor cells were under starvation or chemotherapy, and its elevation promoted survival, motility and angiogenesis." (PMID 23391506, 2012). "The overexpression of HIF-1α has been reported in many tumor types, including colon, breast, gastric, lung, skin, ovarian, pancreatic, prostate and renal carcinomas." (PMID 22211243, 2012). "HIF-1α regulates many genes involved in tumor growth and metastasis, including vascular endothelial growth factor (VEGF) and transforming growth factor-beta (TGF-β)." (PMID 22178269, 2012). "The HIF-1α-mediated transcription plays a critical role in the tumour angiogenesis and growth, though some HIF-1α- independent mechanisms are also known to play an important role in the process." (PMID 23185562, 2012). "Levels of HIF-1α, N-cadherin, and vimentin were upregulated in tumor cells, and E-cadherin was downregulated, under conditions of hypoxia." (PMID 23137165, 2012). "The impact of HIF-1α deletion on tumor-initiating potential was investigated using tumorsphere assays, limiting dilution transplantation and gene expression analysis." (PMID 22225988, 2012). "The factor 1 (SATB1/HIF-1α-AR/ER/BCL2) pattern in the HR-positive tumours revealed an inverse relation between the two groups of markers with the opposite factor loadings." (PMID 22424533, 2012). "We further demonstrate that primary tumor growth and survival from distant metastases are dependent upon epithelial cell intrinsic HIF-1α expression." (PMID 22225988, 2012). "Despite varying HIF-1α levels, tumor cell lines EPLC-272H and H1339 also showed a comparable resistance towards irradiation (SF2: 0.64 for EPLC-272 and 0.76 for H1339)." (PMID 22347438, 2012). "Owing to its important role in the tumour angiogenesis, HIF-1α has been considered as a potential target to control tumour angiogenesis in multiple models." (PMID 23185562, 2012). "Inhibition of mTOR can decrease cancer cell proliferation and survival and reduce tumor-secreted VEGF through inhibition of hypoxia-inducible factor-1α (HIF-1α)." (PMID 21961001, 2012). "Overexpression of p70S6K1 in microvascular endothelial cells enhanced tumor growth and angiogenesis, while HIF-1αsiRNA significantly inhibited tumor growth and angiogenesis, suggesting that endothelial p70S6K1 controls tumor angiogenesis through HIF-1α." (PMID 22505939, 2012). "Xenografted tumours were measured and IκBαM effects on angiogenesis and HIF-1α activation were assessed by immunohistochemistry, western blotting, luciferase reporter assay, and semiquantitative reverse transcription–polymerase chain reaction." (PMID 21119667, 2011). "von Hippel-Lindau-defective tumours have high levels of HIFα and can be subdivided into two groups, tumours with both HIF-1α and HIF-2α (H1H2) and those with only HIF-2α (H2)." (PMID 22015557, 2011). "This gene has been shown to be upregulated by hypoxic conditions and induced by the hypoxia-inducible factor HIF1A, the key transcription factor involved in the response of tumours to hypoxic conditions." (PMID 22067903, 2011). "An increase in HIF-1α levels was observed in both nuclear and cytosolic fractions from tumor tissue, and only in the cytosolic fraction of peritumor tissue when compared to host tissue." (PMID 21489226, 2011). "SCLC exhibits high expression levels of HIF-1α and early hematogenous metastasis to other organs, such as brain, kidney, and liver, which relies on tumor angiogenesis." (PMID 21843314, 2011). "The in vivo study indicated that the tumor formation rate of the HIF-1α transduction group was significantly higher than the rate of the non-transduction and siHIF-1α transduction groups." (PMID 21843314, 2011). "Previous reports of low ATP levels in c4 cells or tumours, and in HIF-1α deficient transformed astrocytes, suggest that loss of either HIF-1α or β leads to a lower tumour energy state." (PMID 21612605, 2011).
tumor (continued). "Combination therapy of sunitinib and RNAi to HIF1α and enolase demonstrates synergistic anti tumor activity." (PMID 21754983, 2011). "There is evidence in the literature that the HIF-1α protein can negatively regulate mitochondrial biogenesis, contributing to the decreased respiration under aerobic conditions seen for many tumor lines." (PMID 21490960, 2011). "In our study, the expression of VEGF-A and the vascular reaction in the transplantation tumor was significantly inhibited after the expression of HIF-1α was downregulated by siHIF-1α." (PMID 21843314, 2011). "Conversely, established cancer cells engineered to over-express myoglobin, thus containing higher intracellular oxygen and lower HIF1-α levels, exhibit a decrease in xenograft tumor growth." (PMID 21589870, 2011). "Further, increased proliferation of c-Myc driven tumors creates a greater environment of tumor hypoxia which in turn activates HIF-1α activity." (PMID 22087262, 2011). "We found that IκBαM overexpression decreased HIF-1α protein expression as well as MVD in xenograft tumours." (PMID 21119667, 2011). "Although our results show that lowering oxygen reduces genomic instability and tumorigenesis in vivo, hypoxic conditions in various systems have also been shown to promote tumor cell growth through HIF1-α induction." (PMID 21589870, 2011). "However, the molecular mechanisms underlying the induction of HIF-1α in tumor cells remain unknown." (PMID 21980400, 2011). "Hif1α also plays a key role in both tumor growth and sensitivity of tumors to chemotherapy and radiotherapy." (PMID 22016813, 2011). "Because the transcriptional activity of AR and HIF-1α was attenuated by panobinostat/everolimus combination in vitro, we asked if these events were critical for the superior anti-tumor activity of panobinostat/combination therapy in vivo." (PMID 22087262, 2011). "Further, cells in which Hif1α is inactivated, including both Hif1α−/− MEFs and tumor cell lines, exhibit increased sensitivity to both chemotherapy and radiotherapy." (PMID 22016813, 2011). "In contrast, HIF2-α has an opposing role to HIF-1α with regard to gene expression, and promotes enhanced tumour growth." (PMID 21285971, 2011). "Significant differences were found for high HIF-1α expression in relation to tumor size (P = 0.007) and HCC with extrahepatic metastasis (P < 0.001), but not in relation to patients’ gender, age, or AFP level (P > 0.05)." (PMID 22224081, 2011). "Taken together, our results demonstrated that miR-21 regulates tumor angiogenesis through inducing HIF-1α and VEGF expression; activates both AKT and ERK pathways for mediating angiogenesis." (PMID 21544242, 2011). "Tumor angiogenesis is required for tumor development and growth in which hypoxia-inducible factor 1α (HIF-1α) plays a pivotal role." (PMID 23554686, 2011). "The oncogenic function of SEPT9 in vivo is still unclear, although SEPT9_v1 in particular has recently been shown to promote tumor growth by inducing angiogenesis via the stabilization of hypoxia-inducible factor-1 alpha (HIF-1α) in a heterotransplant model." (PMID 21831286, 2011). "The IκBαM overexpression suppressed tumour growth, microvessel density, and HIF-1α activation in xenografted tumours." (PMID 21119667, 2011). "Generally, the method used to establish the prognostic significance of HIF-1α and CA IX expression in other tumours is immunohistochemistry." (PMID 21910893, 2011). "Hypoxia-inducible factor 1 (HIF-1α) expression induced by hypoxia plays a critical role in promoting tumor angiogenesis and metastasis." (PMID 21980400, 2011). "Consistent with this, in xenograft assays of CCRCC cells, active HIF-2α is both necessary and sufficient for tumour growth, whereas active HIF-1α is insufficient." (PMID 21386837, 2011). "Reducing Hif1α expression using either genetic or pharmacological approaches both decreases tumor growth and sensitizes tumors to radiation therapy and to chemotherapy." (PMID 22016813, 2011).
tumor (continued). "In contrast, under hypoxia, the prolyl hydroxylases have limited molecular oxygen and are therefore less effective, which enables HIF-1α stabilization, translocation to the nucleus and initiation of gene transcription that benefits the tumor." (PMID 21306611, 2011). "This process is achieved through hydroxylation of two prolyl residues at Pro-402 and Pro-564 in the oxygen-dependent HIF-1α, and leads to recognition by the von Hippel-Lindau tumour suppressor protein and targeting for degradation." (PMID 21291529, 2011). "Immunohistochemistry showed that the frequency of HIF-1α-positive cells was significantly lower in SNU-668IκBαM tumours (mean=16.6%) than in SNU-668Vector tumours (mean=26.2% P=0.001)." (PMID 21119667, 2011). "These cancer stem cells have found to be rich in HIF-1α which is a transcriptional factor and it is activated in the hypoxic conditions in the tumor site and is needed for it survival and proliferation." (PMID 22082307, 2011). "Although the contribution of Hif1α to mediating resistance to radiation therapy varies between cell and tissue types, it is now clear that increased Hif1α levels can have profound impacts on the sensitivity of both normal and tumor cells to cancer therapy." (PMID 22016813, 2011). "Our results support a unifying model in which HIF-1α has a tumour suppressor action in CCRCC, held in check by FIH-1." (PMID 21386837, 2011). "Extracellular acidosis, a common feature in tumours, increases HIF-1α protein accumulation and CA9 transcriptional activity under normoxic conditions." (PMID 21910893, 2011). "Targeting HIF-1α for degradation is currently a vital option in anti-cancer therapy to inhibit tumor neoangiogenesis and glucose transport." (PMID 21949677, 2011). "Sensitivity to CA-074 also characterizes other tumor cell lines indicating preference for cathepsin-B in hypericin mediated HIF-1α turnover." (PMID 21949677, 2011). "Over-expression of HIF-1α and HIF-2α has been documented in several primary tumours and associated metastases, the degree of expression correlates with angiogenesis, resistance to treatment and overall patient outcome." (PMID 22414300, 2011). "Therapeutic anti-angiogenic strategies have been established to limit tumour growth and because of its pivotal role HIF-1α is especially targeted for such treatment." (PMID 21535870, 2011). "On the other hand, it is well recognised that although many of HIF-1α's actions promote tumour growth it can also promote cell cycle arrest and apoptosis." (PMID 21386837, 2011). "This is consistent with previous studies demonstrating that tumor cells containing constitutively high levels of Hif1α are more resistant to both chemotherapy and radiotherapy." (PMID 22016813, 2011). "Animals were then treated with either (2 mg/kg) Digoxin, a cardiac glycoside that has been shown to inhibit HIF-1α synthesis and block tumor formation, or vehicle (Control)." (PMID 21559457, 2011). "Activation of oncogenes or inactivation of tumor suppressors can change signaling pathways and up-regulate HIF-1α expression, leading to HIF-1α activation." (PMID 22224081, 2011). "Our molecular analysis of tumor samples shows that HIF-1α is over-expressed and accumulates in the nucleus of the tumor fraction compared to the peritumor or host fractions." (PMID 21489226, 2011). "This is primarily due to the fact that HIF-1α plays a major role in the development of a characteristic tumor phenotype influencing growth rate, angiogenesis, invasiveness, and metastasis." (PMID 21843314, 2011). "Because of promising in vitro results of our identified HIF-1α inhibitor, we examined tumor growth inhibition due to P3155 treatment." (PMID 21819554, 2011). "In tumor microenvironment, hypoxia stimulates accumulation of HIF-1α protein by decreasing proteasomal degradation." (PMID 22016776, 2011).
tumor (continued). "Our study further supports the previous opinion that HIF-1α is correlated with the development of an aggressive phenotype in some tumor models, and that HIF-1α has been identified as a positive factor for tumor growth." (PMID 21843314, 2011). "Increased tissue hypoxia in the PTGER4 tumours compared with WT tumours is also supported by quantitative RT-PCR analysis demonstrating higher expression of the hypoxia inducible factor HIF1α (P<0.01)." (PMID 21589857, 2011). "Tumor invasion and metastasis are essential for tumor growth and are also directly regulated by HIF-1α." (PMID 21819554, 2011). "HIF-1α is involved in tumor angiogenesis and metastasis by regulating genes involved in response to hypoxia." (PMID 21980400, 2011). "HIF-1α is overexpressed in a broad range of human cancer types and increased levels of HIF-1α activity are often associated with increased tumor aggressiveness and therapeutic resistance." (PMID 21853076, 2011). "In vivo we used an alternative method to study the effect of HIF-1a on angiogenic potential of SCLC by buliding NCI-H446 cell transplantation tumor on the chick embryo chorioallantoic membrane (CAM) surface." (PMID 21843314, 2011). "This was particularly interesting in vivo, where the zinc-inhibitory of HIF-1a was reached inside the xenograft tumor injected in nude mice, meaning that oral zinc administration is able to reach the tumor site and modify the intratumoral HIF-1a expression." (PMID 22202117, 2011). "Their results revealed an increase in HIF-1α level in the early phase of tumor development and a dramatic decrease when the tumor volume was up to 1 cm3." (PMID 22346573, 2011). "In tumor xenografts, decreased HIF-1 activity is usually associated with a slower growing and less angiogenic tumor phenotype, as also assessed by HIF-1α inhibition in a model of inducible RNA interference in vivo." (PMID 21179202, 2010). "In tumour and vascular endothelial cells, both nuclear and cytoplasmic staining of HIF-1α was observed, as well as patchy, diffuse and increased staining adjacent to necrosis, but only nuclear staining of tumour cells was quantified." (PMID 20932344, 2010). "The different roles and expression patterns of HIF1α and HIF2α demonstrate that their specificity is important for tumour propagation and survival." (PMID 20104230, 2010). "Hypoxia-inducible factor-1α (HIF-1α), a critical transcription factor to reduced O2 availability, has been demonstrated to be extensively involved in tumor survival, aggressive progression, drug resistance and angiogenesis." (PMID 20932347, 2010). "It is the expression of HIF-1α in both of these other model systems that is thought to facilitate tumor growth, and over-expression of HIF-2α antagonises this effect." (PMID 20652061, 2010). "By using the tumor sphere forming assay, we demonstrate that HIF-1α plays a role in the survival and self-renewal potential of CSCs." (PMID 20515450, 2010). "In GBMs, HIF-1α is primarily localized in pseudopalisading cells around areas of necrosis and in tumor cells infiltrating the brain at the invasive edge of the tumor." (PMID 20515450, 2010). "In vivo, the effects of ABZ (150 mg/kg, i.p., single dose) on the tumor levels of HIF-1α and VEGF protein and mRNA were investigated by western blotting, RT-PCR and real time-PCR." (PMID 20398289, 2010). "GBM tumors with low HIF1α levels contain fewer bone marrow-derived cells and exhibit lower levels of angiogenesis and tumor growth, as compared to GBM tumors with high HIF1α levels." (PMID 20379377, 2010). "The presence of hypoxia-associated endogenous proteins, such as HIF-1α and CA9, and pimonidazole, an exogenous marker, indicated that both tumour types had hypoxic loci." (PMID 20145613, 2010). "Hypoxia can promote tumor angiogenesis through activation of the transcription factor hypoxia-inducible factor -1α (HIF-1α) which, in turn, enhances production of proangiogenic growth factors." (PMID 20379377, 2010).